ATP5MF-PTCD1 (ATP5MF-PTCD1 readthrough)
Synonyms: ATP5J2-PTCD1
Gene: Protein-coding gene on chromosome 7 (99,419,749 to 99,466,197, reverse strand). Ensembl gene ENSG00000248919.
Genetic constraint (gnomAD): Loss-of-function variants: 59 observed, 66.06 expected, observed/expected ratio (o/e) 0.89, 90% interval 0.72 to 1.11. The upper end of that interval is the gene's LOEUF score, 1.11, which puts it in group 4 of 6, group 1 being the genes least tolerant of losing a copy. Missense variants: 971 observed, 999.36 expected, observed/expected ratio (o/e) 0.97, 90% interval 0.92 to 1.02. Synonymous variants: 431 observed, 431.4 expected, observed/expected ratio (o/e) 1, 90% interval 0.92 to 1.08.